EZH2 (enhancer of zeste 2 polycomb repressive complex 2 subunit)
Diseases named in the same sentence as EZH2 in open-access papers (continued):
Sharing a sentence is not in itself a finding about the gene and the disease.
breast tumor (continued). "A very recent study showed that there was a significantly different expression of both EZH2 and H3K27Me3 in different subtypes of breast tumor." (PMID 24294976, 2013). "Chang and his colleagues have showed that increased EZH2 expression in CD44+ /CD24-/low breast tumor initiating cells correlated with the increased percentage of this specific subpopulation." (PMID 24345883, 2013). "EZH2 promoted expansion of breast tumor initiating cells through RAF1-p-ERK-β-catenin pathway activation." (PMID 24345883, 2013). "To allow direct comparison, we simultaneously performed immunohistochemistry for EZH2 on sections from luminal A, basal-like and BRCA1-mutated breast tumors." (PMID 19709408, 2009). "EZH2 expression was found to be informative in distinguishing renal tumour and normal renal tissue pairs, and also breast tumours from breast normal tissues." (PMID 16638127, 2006). "Our results confirm that overexpression of EZH2 is found in breast tumours compared to the normal breast samples and shows for the first time EZH2 overexpression in renal tumours." (PMID 16638127, 2006). "Moreover, an inverse correlation has been observed between the expression of EZH2 and RORa in breast tumor tissues and their normal counterparts, as the RORa protein expression was level very low in tumors exhibiting high levels of EZH2." (PMID 39769907, 2024). "Interestingly, EZH2 was significantly overexpressed in BRCA1-associated and basal-like breast tumours." (PMID 34287743, 2021). "Further to correlate the MERAV breast tumor expression database, we studied the correlation in the expression of EZH2 and its target genes by quantitative real time PCR following RNA extraction from both tumor and adjacent normal tissues collected from histologically similar primary breast tumors." (PMID 30760814, 2019). "Likewise, the gene expression profile of Ezh2-deleted MECs was most concordant with claudin-low breast tumors." (PMID 30080881, 2018). "EZH2 is essential survival and proliferation of breast tumor initiating cells." (PMID 28410242, 2017). "Overexpression of EZH2 promotes self-renewal of breast tumor initiating cells." (PMID 24294976, 2013). "To assess whether EZH2 was elevated at the protein level in lymph node metastasis, we determined the percentage of EZH2 expressing tumor cells in 8 paired primary breast tumor and lymph node tissue sections using immunohistochemical methods." (PMID 23251464, 2012). "Recently, we and others showed that EZH2 levels are high in breast tumors with a poor prognosis." (PMID 19709408, 2009). "Consistent with our previous observation that EZH2 mRNA and protein levels correlate relatively well, we observed increased EZH2 protein levels in human BRCA1-deficient tumor sections compared with other breast tumors." (PMID 19709408, 2009). "EZH2 is required for the maintenance of embryonic and adult stem cells, is expressed in a relatively small number of cells in the mammary gland, and is only overexpressed in breast tumors with an undifferentiated phenotype." (PMID 19709408, 2009). "We found that breast tumor cells treated with EZH2 small-molecule inhibitors altered the secretome of inflammatory mediators, thus stimulating TAMs infiltration and polarization to a tumor-promoting phenotype, whereas EZH2 genetical deletion rendered the opposite effect." (PMID 36038549, 2022). "NSD3 directly interacted with EZH2 and RNA polymerase II to stimulate H3K36 methylation-dependent transcriptional activation of NOTCH receptor cleavage-associated genes (including Adam12, DLL4, and Notch3), thereby activating Notch signaling to promote breast tumor progression." (PMID 34615858, 2021). "One of the roles of HIF1α is up-regulating EZH2 expression under hypoxia in breast tumor initiating cells (BTICs) that contribute to cancer progression; HIF inhibitors may potentially be effective in suppressing EZH2 oncogenic function in these cells to prevent cancer recurrence." (PMID 25115393, 2014).
breast tumor (continued). "Additionally, immunohistochemical (IHC) staining and quantitative image analysis of whole tissue sections showed a significant increase of EZH2 expressing tumor cells in lymph nodes over paired primary breast tumors, which strongly correlated with tumor cell proliferation in situ." (PMID 23251464, 2012). "However, we did not observe increased EZH2 expression in breast tumors from BRCA2-mutation carriers (data not shown), suggesting that the main oncogenic role of EZH2 is not linked to DNA repair." (PMID 19709408, 2009). "The expression of ABHD11, ADORA2B, E2F1, EZH2, PAICS, SFN and SH3GL1 was significantly higher in grade III than in grade I breast tumors." (PMID 28411283, 2017). "While breast tumors formed by control cells grew rapidly, reflecting the aggressive nature of MDA-MB231 cells, EZH2-KD cells either formed modest tumors with reduced growth rates or failed to initiate tumors altogether." (PMID 23826629, 2013). "Breast cell lines showed downregulation of HDAC1, HDAC2, HDAC5, EZH2, EP300, and PCAF compared to breast tumours." (PMID 16638127, 2006). "In immunohistochemistry no expression of EZH2 was detected in normal breast tumors and grade 1 invasive ductal carcinoma tumors, whereas more than 2.5 fold increase in EZH2 expression was observed in grade 3 breast tumors when compared to grade 2." (PMID 30760814, 2019). "In primary breast tumor tissues a significant negative correlation was evidenced between EZH2 and its target genes which corroborated the correlation observed in online MERAV database." (PMID 30760814, 2019). "Real time PCR performed with RNA extracted from breast tumor tissues further authenticated the existing negative correlation between EZH2 and its target genes." (PMID 30760814, 2019). "Therefore, we stained normal mammary gland tissue as well as breast tumour material for both BMI1 and EZH2 protein expression." (PMID 19099573, 2008). "In the SQ breast tumors, we observed significantly upregulated mRNA levels of the Oct3/4 regulatory network, including ONSS, and several other PTFs, including Nanog, Sall4, Sox2, Sox4, FoxA2, Gata6, Zic2 and HoxB7, as well as Oct3/4 isoform B, polycomb suppressors Bmi1, EzH2, Amigo and Dkk1." (PMID 37298091, 2023). "Moreover, breast tumors in BRCA1-mutation carriers show invariably loss of the other BRCA1 allele, indicating that selection for loss of BRCA1 expression is not achieved by high levels of EZH2." (PMID 19709408, 2009). "EZH2 was the only gene that showed significantly elevated expression at both the transcriptional and translational levels in TNBC compared to non-TNBC subtypes, as well as in breast tumors relative to normal tissues." (PMID 41413688, 2025).
metastatic disease (39 papers, 2010 to 2025). "We report that patients whose PCa tumors expressed high levels of EZH2 at baseline experienced an increased risk of metastatic disease relapse following RT." (PMID 31104332, 2019). "In conclusion, patients with a high level of EZH2 expression in the baseline diagnostic PCa biopsy specimens had an increased risk of metastatic disease recurrence following external beam RT with curative intent." (PMID 31104332, 2019). "EZH2 overexpression was firstly linked to cancer by microarray analysis of prostate and breast cancer where it is associated to aggressive, metastatic disease and to a poor clinical outcome." (PMID 27471434, 2016). "Overexpression of EZH2 is associated with aggressive and metastatic disease in various types of cancer, including CCA." (PMID 24179546, 2013). "Our observations add to this growing field by indicating that dysregulated promoter recruitment of EZH2 to CIITApIV also occurs in MDAMB 435 variants and further indicates EZH2 as a primary culprit in metastatic tumor growth." (PMID 22563434, 2012). "On multivariate analysis, the PCa tissue total EZH2 expression score remained significantly associated with metastatic disease recurrence (P = 0.003), while the PCa tissue EZH2 cytoplasmic expression score fell marginally short of the conventional level of statistical significance (P = 0.053)." (PMID 31104332, 2019). "We hypothesized that increased EZH2 expression is associated with postradiotherapy metastatic disease recurrence, and may promote radioresistance." (PMID 31104332, 2019). "In vivo, experiments showed that combining chemotherapy with PROTAC EZH2 degrader-1 more effectively controlled the growth of leptomeningeal metastatic tumours in nude mice than chemotherapy alone." (PMID 38644473, 2024). "Further studies comparing the expression of BAP1, Survivin and EZH2 in different metastatic tumors and EM should be conducted." (PMID 34257556, 2021). "Prior evidence has demonstrated that the overexpression of EZH2 is a marker of advanced and metastatic disease in many solid tumor." (PMID 33381151, 2020). "Taken together this suggests that EZH2 function promotes post‐RT metastatic disease recurrence in PCa patients, and this is likely to be through mechanisms above and beyond any potential increased radio‐resistance mediated by EZH2 function." (PMID 31104332, 2019). "Increased EZH2 expression or activity is a marker of advanced and metastatic disease in many solid tumors." (PMID 30093632, 2019). "To this end, we employed a transgenic mouse model to examine the effects of Ezh2 ablation at each stage of tumorigenesis from early hyperplastic lesions to invasive metastatic disease." (PMID 29959321, 2018). "In patients with metastatic disease, nuclear EZH2 expression above 5% and up to 50% was an independent predictor of poor CSS." (PMID 20920340, 2010). "Altogether, 520 cases (non-metastatic disease n = 433, metastatic disease n = 87) were scored for expression of EZH2." (PMID 20920340, 2010). "The concordance probability of the Cox regression models including EZH2 was higher compared to models excluding EZH2, for both metastatic and non-metastatic disease." (PMID 20920340, 2010). "In RCC patients with metastatic disease, the concordance probability including EZH2 expression was 68.4%, compared to 63.0% excluding EZH2 expression." (PMID 20920340, 2010). "In patients with RCC metastatic disease, the concordance probability including EZH2 expression was 68.4%, compared to 63.0% in models excluding EZH2 expression." (PMID 20920340, 2010). "EZH2 plays a role in metastatic disease recurrence following radiotherapy." (PMID 35322532, 2022). "Additional changes we observed that we believe are important in the regulation of hMSC homing and invasion based on previous research by our lab and others include increases in gene members of the Glinsky Signature (SUZ12 and EZH2), which determine likelihood of death from metastatic disease." (PMID 24772452, 2013).
metastatic disease (continued). "In these histological groups, EZH2 was superior to Ki-67 in predicting metastatic disease." (PMID 23110793, 2012). "In metastatic disease, nuclear EZH2 expression and histopathological subtype were independent predictive parameters of poor CSS (EZH2: 1-5%: HR 2.63, p = 0.043, >5-25%: HR 3.35, p = 0.013, >25%-50%: HR 4.92, p = 0.003, all compared to 0%: HR 0.36, p = 0.025, respectively)." (PMID 20920340, 2010). "Increasing evidence has revealed that EZH2 has oncogenic properties, as an increased expression of EZH2 augments proliferation and invasion of cancer cells, while depletion leads to a decline in cell proliferation, increased apoptosis, and inhibition of metastatic tumor growth in vivo." (PMID 24999473, 2014). "The Enhancer of zeste homolog 2 (EZH2) methyltransferase, part of the repressive Polycomb Repressive Complex 2 (PRC2) complex has been overexpressed in cancer and especially in metastatic tumors." (PMID 33803458, 2021). "An increased expression of EZH2 mRNA showed a statistically significant positive correlation with stage, Gleason score, LVSI, and metastatic disease." (PMID 32873863, 2020). "In addition, Zhou and colleagues demonstrated that PVT1 could be enriched by enhancer of zeste homolog 2 (EZH2), a marker of an advanced metastatic disease in numerous types of cancer including ATC, which may also contribute to the regulation of TSHR expression." (PMID 32760219, 2020). "Having in the mind that a key event in the progression of BC is the development of lymph node metastases, it is very important to determine prognostic benefit of standard and new molecular markers (ER, HER2, EZH2, CD44) on the occurrence of metastatic disease." (PMID 33235571, 2020). "Notably, Ezh2 has been reported to be necessary for epithelial to mesenchymal transformation (EMT), a process thought to be critical for metastatic disease progression." (PMID 29959321, 2018). "That is, EZH2 similarly to other CC markers e.g. CK7, CK19, claudin 4 does not provide major help in distinguishing cholangiocarcinomas from metastatic tumors, but it does seem to be able to differentiate reactive/hamartomatous biliary structures and benign biliary tumors from malignant ones." (PMID 22809481, 2012). "Moreover, high nuclear EZH2 expression in non-metastatic disease, and nuclear EZH2 expression in metastatic disease are unfavourable independent predictive parameters of CSS." (PMID 20920340, 2010). "In advanced metastatic tumors, transcript levels of INPP4B and EZH2 do not correlate." (PMID 38001678, 2023).
renal cell carcinoma (39 papers, 2010 to 2025). "SF3B3 regulates EZH2 alternative splicing, and its expression is associated with poor outcome in renal cell carcinoma." (PMID 34683129, 2021). "Long non-coding RNAs, such as HOTAIR and MALAT1, promote aggressive renal cell carcinoma by associating with EZH2." (PMID 28410242, 2017). "In this study, we aim to investigate the clinical and prognostic values of EZH2 expression and activity in tumor tissues and improve the risk stratification in patients with renal cell carcinoma after surgery." (PMID 24312307, 2013). "Here, we studied a possible association between EZH2 expression and prognosis in patients with renal cell carcinoma (RCC)." (PMID 20920340, 2010). "Another study has demonstrated that MALAT1 interacts with EZH2 and that the oncogenesis induced by lncRNA MALAT1 can be inhibited by EZH2 depletion in renal cell carcinoma." (PMID 31830649, 2020). "Meanwhile, EZH2 enhanced proliferation and invasion of the renal cell carcinoma cell line ACHN via Wnt / β-catenin pathway." (PMID 28410242, 2017). "Many studies have demonstrated that EZH2 plays crucial roles in the initiation, growth and progression of renal cell carcinoma (RCC)." (PMID 28410242, 2017). "It has been shown that Malat1 promotes aggressive Renal Cell Carcinoma by regulating EZH2 as a ceRNA for miR-205." (PMID 27191262, 2016). "We analyzed EZH2 expression and its activity as indicated by H3K27me3 levels comprising 373 patients with renal cell carcinoma in our institute." (PMID 24312307, 2013). "Furthermore, EZH2 inhibition exerts an antineoplastic effect against renal cell carcinoma through inactivation of large tumor suppressor 1 (LATS1)." (PMID 40243914, 2025). "Moreover, it has been shown that miR-101-3p, via targeting EZH2, plays a tumor suppressor role in renal cell carcinoma." (PMID 35646670, 2022). "Aggressive renal cell carcinoma was promoted by lncRNA MALAT1 via regulation of Ezh2." (PMID 34335862, 2021). "It has also been documented that EZH2 could have the potential to enhance the proliferation abilities of renal cell carcinoma cell line ACHN." (PMID 32308561, 2020). "MALAT1 interacts with EZH2 to suppress E-cadherin (CDH1) expression in renal cell carcinoma." (PMID 26871474, 2016). "EZH2 was associated with pT stage, N status, Fuhrman grade, and TNM stage in renal cell carcinoma." (PMID 25974088, 2015). "Given that EZH2 plays a crucial role in renal cell carcinoma by directly binding to the LATS1 promoter to inhibit its expression and promote tumor growth, we hypothesized that the protective effects of ZLD1039 in UUO-induced renal fibrosis might be mediated by LATS1 expression and activation." (PMID 40478495, 2025). "Enhancer of zeste homolog 2 (EZH2), the catalytic part of the Polycomb repressive complex 2 (PRC2), has a prognostic role in renal cell carcinoma (RCC) and was recently shown to modulate the immune response by reducing tumor cell immunogenicity." (PMID 32303902, 2021). "In renal cell carcinoma, MALAT1 promoted tumor cell proliferation and invasion by interacting with EZH2 and miR-205." (PMID 32393270, 2020). "In renal cell carcinoma, SF3B3 modulates EZH2 alternative splicing to promote carcinogenesis, and SF3B3 could be a potential prognostic factor and therapeutic target in renal cell carcinoma." (PMID 32808488, 2020).